NLRP6 (NLR family pyrin domain containing 6)
Diseases named in the same sentence as NLRP6 in open-access papers (continued):
Sharing a sentence is not in itself a finding about the gene and the disease.
gastric cancer (15 papers, 2017 to 2025). A primary or metastatic malignant neoplasm involving the stomach. "For example, NLRP6 expression was decreased in gastric cancer and obviously associated with Helicobacter pylori infection, lymph node metastasis, tumor stage and survival rate." (PMID 36920176, 2023). "NLRP6 exerted inhibitory effects on gastric cancer cell growth, which implicated the potential therapy application as well." (PMID 37464443, 2023). "Downregulated NLRP6 expression in gastric cancer was significantly associated with overall survival." (PMID 35102195, 2022). "Here, we show that NLRP6 was down-regulated in approximately 75% of primary gastric cancer cases and exhibited significant associations with advanced clinical-stage lymph node metastasis and poor overall survival." (PMID 29340077, 2017). "To further elucidate the role of NLRP6 in gastric cancer, we examined the association between NLRP6 expression and gastric cancer cell proliferation in vitro and in vivo." (PMID 29340077, 2017). "NLRP6 has been associated with other inflammatory gastrointestinal diseases, including Crohn’s disease and gastrointestinal symptoms of graft-versus-host disease, and appears to be protective in the development of gastric cancer." (PMID 41062723, 2025). "Similarly, the association between NLRP6 and several tumors suggests that it may be used as a particular marker for certain tumors, such as colorectal and stomach cancers, to aid in diagnosis." (PMID 37415625, 2023). "Furthermore, low NLRP6 expression was associated with poor prognosis in gastric cancer." (PMID 29340077, 2017). "Although NLRP6 was reported to serve as a tumor suppressor in colorectal cancer, hepatocellular carcinoma, and gastric cancer, it was reported to restore immune evasion and radio-resistance in glioma through ASC/caspase-1/IL-1β axis." (PMID 38678251, 2024). "Patients with low expression of NLRP6 showed a worse OS in multiple cancer types, such as liver cancer, breast cancer, and gastric cancer." (PMID 36151761, 2023). "Overexpression of NLRP6 reduced cell growth, decreased invasion and migration, and promoted cell apoptosis in gastric cancer cells." (PMID 36920176, 2023). "Through AKT/FOXO3 signal transduction, Helicobacter pylori can control the expression of NLRP6 and prevent the growth of stomach cancer." (PMID 37415625, 2023). "Meanwhile, the expression of NLRP7 and NLRP6 was greatly attenuated in gastric cancer tissues than controls." (PMID 37595258, 2023). "Evidence has revealed that OIP5-AS1 aggravated cell growth and migratory ability via interaction with EZH2 and downregulation of NLRP6 in gastric cancer." (PMID 35756672, 2022). "While NLRP6 has been shown to suppress the tumorigenicity of gastric cancer and colorectal cancer, we found that it contributes to the metastasis of SCLC." (PMID 36270983, 2022). "For the inflammasome-independent function, NLRP6 has a protective role in the regulation of NETosis after pneumonia infection, in gastric cancers, in liver diseases, rheumatoid arthritis, certain acute kidney injuries, and intestinal colitis." (PMID 35650327, 2022). "In conclusion, our work showed that NLRP6 significantly inhibited gastric cancer cell proliferation in vitro and in vivo by arresting cell transition from the G1 to S phase." (PMID 29340077, 2017). "To explore the mechanism by which NLRP6 suppresses gastric cancer cell growth, we next investigated the effects of NLRP6 overexpression on cell cycle progression in gastric cancer cells using flow cytometry." (PMID 29340077, 2017). "The current report revealed that NLRP6 is down-regulated in gastric cancer cell lines and tumor tissue samples." (PMID 29340077, 2017). "Our results also showed that NLRP6 suppressed cell cycle progression by regulating the G1/S transition in gastric cancer cells." (PMID 29340077, 2017).
gastric cancer (continued). "Our study provides new insights into the function of NLRP6 and demonstrates that NLRP6 overexpression is a promising strategy for gastric cancer therapy." (PMID 29340077, 2017). "We also assessed NLRP6 expression in gastric cancer tissue samples and found that NLRP6 expression levels were correlated with patient age, local lymph node metastasis, TNM stage, and OS." (PMID 29340077, 2017). "In the present study, we examined NLRP6 expression in gastric cancer tissues and cell lines and found that expression of this protein was dramatically decreased in gastric cancer." (PMID 29340077, 2017). "In most of the tested clinical gastric cancer samples, the mRNA and protein levels of NLRP6 were markedly diminished." (PMID 29340077, 2017). "Epigenetic silencing of the gene encoding NLRP6 enhances cell proliferation and migration during gastric cancer, whereas expression of NLRP6 reduces cancer growth via direct ubiquitination and degradation of the molecular chaperone GRP78 in gastric cancer." (PMID 41062723, 2025). "Moreover, decreased level of NLRP6 was correlated with unfavorable prognosis in patients with head and neck squamous cell carcinoma (NHSCC), revealing the tumor suppressive role of NLRP6 in gastric cancer and NHSCC." (PMID 36920176, 2023). "In gastric cancer, NLRP6 can bind through its PYD domain to the substrate-binding domain (SBD) of the 78 kDa glucose-regulated protein (GRP78), which in turn promotes the ubiquitination and degradation of GRP78 and thus reduces its expression and inhibits gastric cancer growth." (PMID 35650327, 2022). "Therefore, to further assess the mechanism by which NLRP6 suppresses gastric cancer proliferation, we next analyzed the expression of the related proteins by Western blotting." (PMID 29340077, 2017). "Moreover, the level of NLRP6 expression can potentially be used as a prognostic determinant in gastric cancer patients." (PMID 29340077, 2017).
colorectal cancer (13 papers, 2013 to 2024). A primary or metastatic malignant neoplasm that affects the colon or rectum. "Nlrp3−/−, Nlrp6−/−, Nlrc4−/−, Nlrp1−/−, Nlrx1−/− and Nlrp12−/− mice show increased susceptibility to inflammation-induced colorectal cancer as compared to wild-type mice." (PMID 31186453, 2019). "Future studies should include determining if mutations in NLRP6 are correlated with colorectal cancer and dysbiosis in humans, specifically with the increased Prevotellaceae." (PMID 24273542, 2013). "Inosine, one of the upstream regulators of NLRP6-deficient CD103+ Bregs, can also be produced by the microbiota and is important in inhibition of severe autoimmunity, and improving the efficacy of checkpoint inhibitor therapy in colorectal cancer." (PMID 36911699, 2023). "Hence, the protein downregulation of NLRP6, caspase-1 or IL-18 in epithelial tumor cells was correlated with a poor clinical outcome for colorectal cancer patients." (PMID 33255437, 2020). "If a correlation exists between NLRP6 and colorectal cancer in humans, NLRP6 may serve as a valuable biomarker and therapeutic target." (PMID 24273542, 2013). "As with NLRP6, NOD1 is also a member of the NOD-Like Receptor (NLR), and it could modulate the immunosuppressive activity of myeloid cells in colorectal cancer." (PMID 36823654, 2023). "Although the expression of NLRP6 is essential to prevent colorectal cancer in murine models, gene expression analysis of colorectal cancer patients shows no change in the expression of NLRP6." (PMID 33910012, 2021). "Similarly, lack of NLRP6-mediated control of the microbiota induced non-alcoholic fatty liver disease and obesity in mice and increased colorectal cancer, all of which were transmissible through microbiota transfer to wild-type mice." (PMID 24381573, 2013). "In addition, NLRP12-deficiency led to enhanced colon inflammation and colorectal cancer development due to increased (non-canonical) NF-κB and ERK activation, similar to what was observed previously for NLRP6." (PMID 24381573, 2013). "NOD1 and NOD2 expression were enhanced in colorectal cancer, and NLRC5, NLRP6 and NLRP12 had no significant changes compared to the controls." (PMID 34571825, 2021).
glioma (12 papers, 2021 to 2024). A benign or malignant brain and spinal cord tumor that arises from glial cells (astrocytes, oligodendrocytes, ependymal cells). "Consistent with the in vitro results, we found that NLRP6 overexpression promoted glioma progression, while NLRP6 deficiency inhibited tumour growth in vivo." (PMID 37770465, 2023). "Furthermore, NLRP6-induced glioma progression was abolished when PTEN or PIK3R1 was deficient." (PMID 37770465, 2023). "In 2019, a clear structure of NLRP6 was elucidated using cryo-electron microscopy (cryo-EM) and crystallography, and the molecular mechanism underlying the assembly and activation of NLRP6 was elucidated, along with functional studies being undertaken in gliomas." (PMID 37723542, 2023). "The recent report indicated that SP1 transcriptionally activates NLRP6 inflammasome to trigger immune evasion and radioresistance in glioma cells." (PMID 38166970, 2024). "Fewer reports of NLRP6 in glioma have been made compared to NLRP3 and NLRC4, but some progress has been made in recent years." (PMID 37723542, 2023). "NLRP6 transcriptionally induced by SP1 affects the subsequent increase in NLRP6 inflammasome activation and further causes immune escape from CD8+ T cells and radiation resistance of glioma cells." (PMID 37723542, 2023). "NLRP6, which shows robust expression in gliomas, also belongs to the NLR family, similar to NLRP3 and NLRC4." (PMID 37723542, 2023). "SP1 transcriptionally activated NLRP6 to induce radioresistance in glioma cells." (PMID 38589918, 2024). "Importantly, the functions of the NLRP6 inflammasome in gliomas lead to a rather aggressive acceleration of carcinogenesis." (PMID 37723542, 2023). "In addition, the malignancy of gliomas has a positive correlation with the inflammatory response, and a significant decrease in the inflammatory response via the inhibition of NLRP6 through miR-331-3p was observed in microglial cell lines." (PMID 37723542, 2023). "Additionally, miR-331-3p, SP1 inhibitor, and PPAR-γ inhibitors can prevent the expression of NLRP6 in glioma." (PMID 37723542, 2023). "So far, the roles of NLRP6 in glioma have been unveiled, and a rough outline of its overall landscape has been obtained; however, numerous aspects remain to be solved, such as the role in specific major cell types and exosomes, including the regulatory signaling pathway." (PMID 37723542, 2023). "In the present study, NLRP6 protein level is a rate-limiting factor for p85α degradation in glioma." (PMID 37770465, 2023). "Although U87 cells may represent an unreliable HGG model, this study suggested that SP1 may interact with the NLRP6 inflammasome to increase the malignancy, immune evasion, and radioresistance of glioma cells." (PMID 34445646, 2021). "Compared with normal tissues, except for MEFV, NLRP6, NLRP9, RIPK3, and ZBP1, the expression levels of the remaining genes were relatively high in glioma tissues." (PMID 37501725, 2023). "The increase of NLRP6 expression could reduce p85α protein level and enhance PI3K/AKT pathway activation, leading to glioma tumorigenesis." (PMID 37770465, 2023). "The relationship between specific protein 1 and NLRP6 inflammasome in the research of glioma and papillary thyroid cancer (PTC) improves the malignant behavior, immunological avoidance, and radiation resistance of glioma cells." (PMID 37415625, 2023). "Disruption of the NLRP6/p85α interaction could stabilize p85α, inhibit the PI3K/AKT pathway, and suppress tumour growth, indicating a promising therapeutic strategy against glioma." (PMID 37770465, 2023). "However, the NLRP6 inflammasome does not play a beneficial role in gram-positive infections, GVHD, ulcerative colitis, glioma, ischemia/reperfusion brain injury, or liver infections with parasites." (PMID 35650327, 2022).
Obesity (11 papers, 2020 to 2026). Accumulation of substantial excess body fat. "Genetically driven dysbiosis, such as a deficiency in NACHT, LRR, and PYD domains protein 6 (NLRP6), exacerbates steatohepatitis, while obesity-induced dysbiosis promotes HCC formation through the cytotoxic effects of secondary bile acids." (PMID 39931363, 2025). "Our data suggest that to increase the reduced intestinal expression of NLRP6 in patients with obesity-associated T2D may be a potential therapeutic intervention." (PMID 38315242, 2024). "NLRP6, a microbe-recognizing inflammasome protein, is highly expressed by intestinal epithelial cells and can alter susceptibility to cancer, obesity and Crohn’s disease; however, the role of NLRP6 in modulating susceptibility to autoimmune diabetes, was previously unknown." (PMID 36911699, 2023). "Nlrp6 mRNA level in the gut was decreased in patients with obesity and type 2 diabetes and in rats with diet‐induced obesity." (PMID 40526091, 2025). "NLRP6 was recently shown to protect from intestinal damage in patients and rodents with obesity and type 2 diabetes." (PMID 40526091, 2025). "SWELL1 and key markers of inflammation (NLRP3, NLRP6, IL1B, IL18 and IL8) were also upregulated in VAT in obesity and T2D being significantly associated (P < 0.01) with PIEZO1 levels." (PMID 39707172, 2024). "Patients with obesity and T2D exhibited decreased (P < 0.05) jejunum gene expression levels of NLRP6 and its main effector IL18 together with increased (P < 0.05) mRNA levels of inflammatory markers." (PMID 38315242, 2024). "Of the 22 human NLRs known to date, six proteins (NLRP3, NLRP6, NOD1, NOD2, NLRC5 and NLRP12) have been described to be associated with obesity and low-grade inflammation and one (NLRP3) with postprandial inflammation." (PMID 37239938, 2023). "Additionally, decreased (P < 0.05) mRNA levels of Nlrp1, Nlrp3 and Nlrp6 in the small intestinal tract obtained from rats with diet-induced obesity were found." (PMID 38315242, 2024). "Additionally, NLRP6 was a protective factor in the progression of non‐alcoholic fatty liver disease and obesity." (PMID 35651286, 2023). "NLRP6 also protects against the advancement of nonalcoholic fatty liver disease and obesity." (PMID 36685920, 2022). "NLRP6 was the sensor component of NLPP3 inflammasome which could enhance muscular dystrophy and was strongly associated with obesity." (PMID 32801562, 2020). "Besides, Roux-en-Y gastric bypass (RYGB) has also been shown to prime NLRP6, through up-regulation of NLRP6 expression upon exposition of intestine cells to microbiota-related metabolites, taurine, and histamine, resulting from intestinal permeability due to obesity." (PMID 38644450, 2024). "We detected increased mRNA levels of NLPR3 (P = 0.002), NLRP6 (P < 0.001) and its effectors IL1B (P = 0.002), IL8 (P = 0.047) and IL18 (P = 0.006) in VAT of patients with obesity and with obesity and T2D." (PMID 39707172, 2024). "Neither the pro-inflammatory factors TNF-α and IL-1β nor the secretome from patients with obesity (that is enriched in inflammatory mediators) exhibited an effect on the modulation of the NLRP6 inflammasome in the human enterocyte cell line CCL-241." (PMID 38315242, 2024).
hepatocellular carcinoma (10 papers, 2022 to 2026). A malignant tumor that arises from hepatocytes. "Research on periodontal disease and hepatocellular carcinoma has suggested that NLRP6 might be involved in pyroptosis." (PMID 37176030, 2023). "Nlrp6 knockout ameliorated the deleterious effect of C. albicans, suggesting that intestinal NACHT, LRR and PYD domains-containing protein 6 (NLRP6) mediates the effect of mycobiota on tumor growth in mouse hepatocellular carcinoma." (PMID 41087644, 2025).